CDK2 (cyclin dependent kinase 2)
Diseases named in the same sentence as CDK2 in open-access papers (continued):
Sharing a sentence is not in itself a finding about the gene and the disease.
Alzheimer disease (4 papers, 2022 to 2025). A progressive, neurodegenerative disease characterized by loss of function and death of nerve cells in several areas of the brain leading to loss of cognitive function such as memory and language. "Another study demonstrated that cyclin-dependent kinase 2 (Cdk2) phosphorylation of tau at Alzheimer’s disease-associated sites accelerated condensation." (PMID 37927337, 2023). "CDK2 itself does not cause epilepsy directly, but is implicated in mechanisms that contribute to epilepsy, particularly in those with Alzheimer’s disease (AD)." (PMID 41386826, 2025).
asthma (4 papers, 2020 to 2024). "The results of molecular docking, qRT-PCR, and Western blot analysis suggest that PARP1, CDK2, and MAPK1 might play important roles in the treatment of asthma." (PMID 35399637, 2022). "Moreover, genes related to growth and development (e.g., ERBB2, CDK2, PGAP3) were upregulated in asthma, which led to the feature of airway remodeling in the asthmatic monkeys." (PMID 36439114, 2022).
atherosclerosis (4 papers, 2016 to 2017). A disease characterized by the build-up of fatty material and calcium deposition in the arterial wall resulting in partial or complete occlusion of the arterial lumen. "CDK2 negatively regulates neointimal thickening in animal models of restenosis and atherosclerosis, and its expression in human neointimal lesions is consistent with a protective role." (PMID 27251057, 2016). "In this study, we demonstrated that Kiom-18, a novel composition of C. cassia, P. densiflora, C. longa and G. glabra, prevents atherosclerosis through the anti-proliferative effect on VSMCs via the regulation of cell cycle-related proteins such as CDK2, CDK4, cyclin D1, cyclin E1, Rb, and PCNA." (PMID 27465365, 2016).
cholangiocarcinoma (4 papers, 2015 to 2022). A carcinoma that arises from the intrahepatic biliary tree (intrahepatic cholangiocarcinoma) or from the junction, or adjacent to the junction, of the right and left hepatic ducts (hilar cholangiocarcinoma). "In cholangiocarcinoma cells, PTK7 depletion affected the level of cell-cycle related proteins, increasing Cdk2, Cdk4, Cdk6, and cyclin D1 and decreasing p16, p21, and p27, whereas it increased mitochondrial-dependent apoptosis." (PMID 25962058, 2015).
colitis (4 papers, 2020 to 2024). Inflammation of the colon. "Moreover, CDK2-deficient Tregs are more suppressive and ameliorate colitis in an in vivo mouse model of IBD; this is primarily because the N-terminal amino acid sequence of Foxp3, which contains four CDK substrate motifs and is phosphorylated by CDK2, leading to Foxp3 instability." (PMID 34759371, 2021). "However, aside from these markers, there were no noteworthy disparities in the expression levels of liver regeneration markers, such as Cyclin D, cdk2, cdk4, and eNOS, between DSS-exposed colitis mice and those subjected to ZPE treatment." (PMID 39458516, 2024).
corticotroph adenoma (4 papers, 2018 to 2024). "Martins and colleagues conducted a study to investigate the USP8 variant and its contribution to gene expression of cell cycle regulators including P27/CDKN1B, CCNE1, CCND1, CDK2, CDK4, and CDK6 in 32 corticotroph adenoma." (PMID 38862897, 2024).
cutaneous melanoma (4 papers, 2020 to 2025). A primary melanoma arising from atypical melanocytes in the skin. "Moreover, the knockdown of CDK2 through the CRISP/Cas9 approach induced apoptosis in cutaneous melanoma cells." (PMID 39820173, 2025). "In cutaneous melanoma, the effects of Dinaciclib correlated neither with the presence of BRAS or NRAS mutations, nor with CDK2 levels." (PMID 35326726, 2022).
cyst (4 papers, 2017 to 2023). A sac-like closed membranous structure that may be empty or contain fluid or amorphous material. "A signal transducer, CDK2, can induce cyst formation and localize to cytoplasm in Giardia." (PMID 37095576, 2023). "Knockdown of mlf gene also led to a decrease in the levels of CWP1, MYB2, WRKY, PAX1, and CDK2 proteins and cwp1-3, myb2, wrky, pax1, and cdk2 gene expression and cyst formation, suggesting a positive role of MLF in inducing cwp1-3, myb2, wrky, pax1 and cdk2 genes and cyst formation." (PMID 30856211, 2019). "Previously, the role of the cyclin-dependent kinase Cdk2 (GL50803_16802) during encystation has been investigated and has been proven to affect phosphorylation of Myb2 and the expression of CWP-1 and -2 and cyst formation." (PMID 34946882, 2021).
invasive breast carcinoma (4 papers, 2008 to 2024). A carcinoma that infiltrates the breast parenchyma. "Overall, the positive ratio of expression of CDK2-AP1 was reduced successively in normal breast tissue, DCIS, invasive breast cancer and relapsed breast cancer, in contrast to CDK2 and CyclinD1 expression." (PMID 25550687, 2014). "The clinicopathological significance of CDK2 in ductal carcinomas in situ (DCIS) and early-stage invasive breast cancers (BCs) remains largely unknown." (PMID 38732271, 2024). "However, the clinicopathological significance of CDK2 in clinical breast ductal carcinoma in situ (DCIS) or early invasive breast cancer (IBC) has not been described previously." (PMID 38732271, 2024).
leiomyoma (4 papers, 2014 to 2022). A well-circumscribed benign smooth muscle neoplasm characterized by the presence of spindle cells with cigar-shaped nuclei, interlacing fascicles, and a whorled pattern. "TN was also reported to suppress the proliferation of cultured human leiomyoma cells by inhibiting cell cycle modulators, such as cyclin-dependent kinase 2 (CDK-2)." (PMID 25295247, 2014). "In addition, tranilast was recently shown to suppress transcription of COL3A1 and CDK2 through regulation of the microRNA miR-29c in leiomyoma smooth muscle cells." (PMID 29666462, 2018). "In a recent study, miR-29c, miR-200c, and miR-93 3 were reported to regulate cell proliferation of leiomyoma via their effects on key cell cycle regulatory proteins including E2F transcription factor 1(E2F1), Cyclin D1 (CCND1), and CDK2 in vitro." (PMID 31159158, 2019).
liver fibrosis (4 papers, 2019 to 2023). "Accordingly, poor survival and reduced proliferation capacity of HSCs due to Ccne1 or Cdk2-deficiency is one possible mechanism to explain the substantial reduction of liver fibrosis in our study." (PMID 37620309, 2023). "Transition of hepatic stellate cells (HSCs) from a quiescent to an activated state is a sign of the onset of liver fibrosis, and this process is controlled by E-type cyclins (CcnE1, CcnE2) and their associated cyclin-dependent kinase 2 (Cdk2)." (PMID 30923657, 2019). "Thus, HSC-specific targeting of Ccne1 or Cdk2 in patients with liver fibrosis and high risk for HCC development could be therapeutically beneficial." (PMID 37620309, 2023). "In summary, we provide evidence that Ccne1 expression in a small population of HSCs is sufficient to trigger extensive liver fibrosis and hepatocarcinogenesis in a Cdk2-dependent manner." (PMID 37620309, 2023). "Their results show that arctigenin elevates the expression of p27(Kip1) protein through inhibition of Akt and improvement of FOXO3a, resulting in the inhibition of CDK2 kinase activity for liver fibrosis." (PMID 30884781, 2019). "Importantly, the deletion of Cdk2 in HSCs also resulted in attenuated liver fibrosis after chronic CCl4 treatment." (PMID 37620309, 2023). "We provide evidence that the inactivation of Ccne1 only in HSCs is sufficient to substantially reduce liver fibrosis but also HCC development in CCl4-mediated murine injury models, which is at least partially dependent on its canonical kinase subunit CDK2." (PMID 37620309, 2023). "Evidence also suggested that HD (200 mg/kg) inhibited the DEN-induced liver fibrosis and tumor growth through the upregulation of phosphatidylinositide 3-kinases (PI3K), serine/threonine kinase (AKT), cyclin-dependent kinase 2 (CDK-2) signaling pathway." (PMID 32863858, 2020).
renal failure (4 papers, 2014 to 2025). "The increased activity of CDK-2 has been discovered in adverse renal diseases, such as renal failure during sepsis and IgA nephropathy." (PMID 29950996, 2018). "A diagnostic nomogram model was constructed on the two signature genes, CDK2 and CCND1, to predict the likelihood of HF and KF occurrences via either training set or validation set, resulting in a high level of precision in forecasting heart and kidney failure risk." (PMID 39351221, 2024). "This study identifies CDK2 and CCND1 as novel biomarkers linking cell cycle regulation and inflammation in heart and kidney failure." (PMID 39351221, 2024). "Consequently, we propose that CDK2 and CCND1 may play a crucial role in immune response, potentially through signaling pathways involving neutrophils, monocytes, and resting NK cells, which are related to the pathophysiology of both heart and kidney failure." (PMID 39351221, 2024).
Sepsis (4 papers, 2018 to 2025). Sepsis is defined as life-threatening organ dysfunction caused by a dysregulated host response to infection. "Furthermore, miR-21-3p was shown to regulate energy metabolism via AKT/Cyclin-dependent kinase 2 (CDK2)-FOXO1 in a sepsis-induced rat AKI model, while it was unclear whether the regulation was protective or harmful for a long-term prognosis." (PMID 37761260, 2023). "In a mouse model of sepsis induced by cecal ligation and puncture (CLP), global or myeloid-specific genetic knockout of either CDK2 or ACOD1 significantly improved survival, attenuating systemic inflammation, organ dysfunction, and coagulopathy." (PMID 40703506, 2025). "GeneWalk analysis identified potential regulatory genes involved in sepsis, including IL1B, CDKN1A, CDK2, CSF3, and IL1R2, which were included among the SRGs." (PMID 40303348, 2025). "Pharmacological inhibition of CDK2, a kinase upstream of ACOD1, with dinaciclib has replicated these benefits in CLP and other clinically relevant sepsis models (e.g., E. coli and S. pneumoniae), suggesting that targeting the CDK2-ACOD1 axis may be a promising therapeutic strategy." (PMID 40703506, 2025).
serous ovarian carcinoma (4 papers, 2018 to 2023). "Cyclin-dependent kinase 2 (CDK2) was reported as an ideal target for high-grade serous ovarian cancer (HGSC) with elevated CCNE1 expression." (PMID 29433585, 2018). "We demonstrate that combining a selective cyclin-dependent kinase 2 inhibitor with a DNA damaging agent could be a powerful tool in the clinic for high-grade serous ovarian cancer." (PMID 37519629, 2023). "CDK2-mediated phosphorylation of EZH2 at T416 activates EZH2 to silence target genes—ERα gene (ESR1), leading to in high-grade serous ovarian carcinoma (HGSOC) and TNBC." (PMID 37803297, 2023).
small cell lung carcinoma (4 papers, 2017 to 2025). Small cell lung cancer (SCLC) is a highly aggressive malignant neoplasm, accounting for 10-15% of lung cancer cases, characterized byrapid growth, and early metastasis. "CDK2, is identified in the small-cell lung cancer pathway by the KEGG pathway (PATH:ko05222), and it plays a role in the cell cycle." (PMID 40088196, 2025). "In sum, our findings suggest IL-15 suppresses NCI-H446 small cell lung cancer cell proliferation through cell cycle arrest mediated by cyclin E and CDK2." (PMID 29296227, 2017). "Downstream target proteins including LAMC1, LAMC3, CDK2 and FN1 were enriched in the cancer‐related pathways in small cell lung cancer." (PMID 35668574, 2023).
brain tumor (3 papers, 2020 to 2022). "The water extract from G. lucidum inhibited cell proliferation in a dose- and time-dependent manner, and it induced mitochondria-mediated apoptosis and cell cycle arrest at S phase via the cyclin-CDK2 pathway in human brain tumor cells." (PMID 32781747, 2020). "The dual role of CDK2 in MYCN-driven brain tumors was shown to successfully target MYCN-driven MB in 2018." (PMID 33585252, 2020).
Burkitt lymphoma (3 papers, 2007 to 2018). A rare form of malignant mature B-cell non-Hodgkin lymphoma. "Remarkably, miR-103 inhibits CDK2 and cyclin E1 in ALL and Burkitt's lymphoma cells as in the mouse intestinal crypt." (PMID 27888798, 2017). "However, MYC is not the only HSP90 client protein in Burkitt lymphoma, and so it is possible that the mechanism of action is not exclusively through MYC, but involves the destabilization of cell cycle regulators such as CDK2 and CDK4 directly due to loss of HSP90 function." (PMID 30453475, 2018).
chronic lymphocytic leukemia (3 papers, 2020 to 2025). "Similarly, dinaciclib is a highly potent CDK inhibitor with selectivity for CDK1, CDK2, CDK5, and CDK9 in phase III clinical trials for the treatment of refractory chronic lymphocytic leukemia." (PMID 32412527, 2020).
COVID-19 (3 papers, 2021 to 2024). A disease caused by infection with severe acute respiratory syndrome coronavirus 2. "Interestingly, when it comes to potential COVID-19 treatment, most literature data have been focused on CDK2, but not CDK5, identified by our study." (PMID 37685932, 2023).
embryonal carcinoma (3 papers, 2005 to 2016). A non-seminomatous malignant germ cell tumor characterized by the presence of large germ cells with abundant cytoplasm resembling epithelial cells, geographic necrosis, high mitotic activity, and pseudoglandular and pseudopapillary structures formation. "In our previous report we compared the response to CDK2 inhibitors in hES and embryonal carcinoma (hEC) cells and showed the different sensitivity of these cell types." (PMID 27247576, 2016). "In this study we investigated the effects of the small molecular agent NU6140 (inhibits CDK2 and cyclin A interaction) on human embryonic stem (hES) cells and embryonal carcinoma-derived (hEC) cells via the expression of transcription factors responsible for pluripotency." (PMID 25477962, 2014). "In addition, in the embryonal carcinoma cell line NTERA-2, cyclin E-dependent CDK2 activity, but not cyclin D3-dependent CDK4 activity, was suppressed as a result of hexamethylene-bisacetamide-induced differentiation." (PMID 16012517, 2005).
Ewing sarcoma (3 papers, 2016 to 2026). A small round cell tumor that lacks morphologic, immunohistochemical, and electron microscopic evidence of neuroectodermal differentiation. "Cyclin-E binds CDK2 to induce G1/S transition, whereas p21 and p27 repress cyclin-E/CDK2 complex to inhibit the processes; therefore these results indicated that inhibition of SOX2 in Ewing’s sarcoma cells was induced by repression of cyclin-E and activation of p21 and p27." (PMID 26969300, 2016).
female infertility (3 papers, 2019 to 2023). Diminished or absent ability of a female to achieve conception. "Cdk1 and Cdk2 expression has been observed in mouse oocytes, and oocyte-specific deletion of Cdk1 and Cdk2 showed that only the loss of Cdk1 prevents the resumption of meiosis in oocytes, leading to female infertility." (PMID 37686466, 2023). "A Cdk2 KO causes both male and female infertility, due to both spermatocytes and oocytes arresting at prophase I." (PMID 32731332, 2020). "Furthermore, Cdk1 KO, but not Cdk2, resulted in female infertility due to a failure in the resumption of meiosis in oocytes." (PMID 30913540, 2019).
gastrointestinal stromal tumor (3 papers, 2020 to 2025). "Additionally, studies on gastrointestinal stromal tumor (GIST) cell lines with intact RB revealed that the dual inhibition of CDK2 (PF-06873600, CDK2 inhibitor II) and CDK4/6 (palbociclib or abemaciclib) effectively arrested cells in the G1 phase." (PMID 40282469, 2025).
HCMV infection (3 papers, 2009 to 2023). "Taken together, these results indicate that both the viral protein kinase pUL97 and the cellular kinase Cdk2 were involved in SAMHD1 T592 phosphorylation during HCMV infection." (PMID 32986788, 2020). "HCMV infection activates cyclin E- and cyclin B-dependent kinase activity (but not cyclin D- or cyclin A-dependent kinase activity), and cyclin E/Cdk2 complexes are known to phosphorylate Rb." (PMID 19146698, 2009). "Next, we investigated whether SIRT2 functions through the regulation of CDK2 activity during HCMV infection." (PMID 37916830, 2023). "Although cellular Cdks don't appear to play a role in the phosphorylation of Rb during HCMV infection, their activity is required for efficient viral replication as evidenced by reduced viral yields in the presence of a Cdk inhibitor such as roscovitine or a dominant-negative Cdk2." (PMID 19146698, 2009). "In studying the provirus effect of SIRT2 during HCMV infection, we have also identified and characterized an SIRT2-regulated acetylation site on CDK2." (PMID 37916830, 2023). "We found CDK2 to interact with SIRT2 in uninfected cells and at early time points of HCMV infection." (PMID 37916830, 2023).
hearing loss (3 papers, 2018 to 2022). "In this study, we identify a regulatory role of CDK2 in aminoglycoside antibiotic-induced sensory hair cell death, revealing a promising target for preventing clinical drug-induced hearing loss." (PMID 36311033, 2022). "Recently, we identified several CDK2 inhibitors that protect against cisplatin- and noise-induced hearing loss." (PMID 33268358, 2020). "Our experiments have revealed the proapoptotic function of CDK2 in postmitotic cochlear cells and have identified promising therapeutics for preventing hearing loss." (PMID 29514916, 2018). "Our experiments have revealed the proapoptotic role of CDK2 in postmitotic cochlear cells and have identified a promising preventive treatment for cisplatin- and noise-induced hearing loss." (PMID 29514916, 2018). "Previously, we have identified CDK2 inhibitors as candidate therapeutics for hearing loss." (PMID 33268358, 2020). "Modifications of the treatment regimens, additional optimization of the delivery methods via the use of hydrogels, and structural modifications of the compounds via medicinal chemistry could ensure even better results with CDK2 inhibitors in treating hearing loss in humans." (PMID 29514916, 2018). "Our studies identify candidate therapeutics for hearing loss and highlight the key roles of BRAF/MEK/ERK and CDK2 pathways in postmitotic cochlear cells." (PMID 33268358, 2020).
hepatitis B (3 papers, 2020 to 2022).
Hyperglycemia (3 papers, 2013 to 2025). An increased concentration of glucose in the blood. "Further downstream of these events, the increased expression of cell cycle-associated proteins such as CDK2 and Cyclin D1 can accelerate progression through the cell cycle thus leading to an aberrant increase in cell proliferation under hyperglycemia." (PMID 24260287, 2013). "However, in parallel with previous studies, we demonstrate enhanced expression of CDK2 and Cyclin D1 upon exposure to hyperglycemia, indicating an accelerated cell cycle in response to hyperglycemia." (PMID 24260287, 2013).